INS (insulin)
Diseases named in the same sentence as INS in open-access papers (continued):
Sharing a sentence is not in itself a finding about the gene and the disease.
Obesity (continued). "During the development of obesity, storage of excess amounts of triacylglycerol in adipose tissue is associated with altered release of adipokines and cytokines that control local and systemic inflammatory processes and interfere with insulin signalling." (PMID 26940592, 2016). "Collectively, these observations prompted us to examine whether obesity-independent hyperglycemia caused by insufficient insulin levels (Type 1 diabetes) alters the outcomes of B. burgdorferi infection in mouse models of Lyme disease." (PMID 27340827, 2016). "In conclusion, our results suggest that dysregulation of skeletal muscle insulin sensitivity is an early and central event of obesity-associated IR development and the principal feature to characterize insulin-resistant compared to insulin-sensitive post-menopausal women with grade I obesity." (PMID 27111539, 2016). "Insulin and leptin are suggested links between obesity and breast cancer risk, as they may contribute to the malignant transformation of breast epithelial cells and cancer progression." (PMID 27415018, 2016). "The aim of this study was to determine the impact of a perinatal high fat diet on energy metabolism and on leptin as well as insulin sensitivity, early in life and at adulthood in two strains of rats presenting different susceptibilities to diet-induced obesity." (PMID 27618559, 2016). "This diet-enhanced Ras and Src co-activated tumor model has also been used to investigate whether increased insulin levels underlie the obesity-mediated promotion of malignant tumors." (PMID 27604692, 2016). "Furthermore, HFD feeding caused strikingly increased levels of obesity-related metabolic parameters including fasting blood glucose, serum insulin, epididymal adipose tissue masses, and liver indices, and decreased serum adiponectin level in mice." (PMID 28029143, 2016). "One of the major determinants of obesity-associated metabolic complications is the location of the storage of excess fat, with fat accumulation in metabolically active tissues such as muscle and liver leading to insulin resistance of these tissues." (PMID 27591854, 2016). "Moreover, accumulation of DNA mutations, as in APC, KRAS, NRAS, BRAF, or PIK3CA, and insulin secretion sets obesity as a multifactor phenomenon involved in CRC initiation and aggressive development." (PMID 26801617, 2016). "It has been suggested that the mechanism behind the increased risk of obesity associated with high protein intakes during infancy may be the protein-associated stimulation of insulin and IGF-1 release." (PMID 27271662, 2016). "Therefore, in this study we evaluated glycaemic profiles using a CGM sensor in children with overweight and obesity in free-living conditions, and examined the association between glycaemic profiles with insulin resistance and cardiovascular risk parameters." (PMID 27534260, 2016). "These possible effects might have a long-term preventive potential as diet induced enhancement of insulin secretion in infancy associated with increased early weight gain as well as higher long-term risk of obesity and associated disorders." (PMID 26987056, 2016). "Obesity is often associated with resistance to vascular actions of insulin." (PMID 27562094, 2016). "The hormonal effects of insulin are one potential mechanism by which obesity and cancer could be linked." (PMID 27604692, 2016). "Overall, our results suggest that diet-induced maternal obesity leads to increased susceptibility to obesity and impairment of insulin signalling in offspring in early and late life that cannot be reversed by SC consumption, but can be aggravated by HFD re-exposure." (PMID 27479001, 2016). "The positive effect of low-carbohydrate diets on CVD risk factors (obesity, blood lipids, blood glucose, insulin, blood pressure) is already apparent in short-term clinical trials lasting 3–36 months and low-carbohydrate diets also appear superior to low-fat diets in this regard." (PMID 27680091, 2016).
Obesity (continued). "Several hypotheses concerning the underlying mechanisms that link obesity and cancer have been proposed, including hormonal effects (involving insulin), metabolic effects (involving glucose) and inflammation, as well as the role of gut microbial metabolites." (PMID 27604692, 2016). "Therefore, while we did not observe consistent effects of reducing Ins2 gene dosage on circulating insulin and obesity in male mice, in general, these data support the concept that reduced insulin levels are associated with attenuated body weight and obesity." (PMID 27055260, 2016). "Excess caloric consumption and obesity are suggested to cause a sustained systemic inflammation, which impairs the insulin-secretory capacity of pancreas and insulin sensitivity of peripheral tissues, including fat, muscle, and liver, thereby contributing to the development of T2D." (PMID 28029143, 2016). "Obesity is associated with increased insulin levels, and induces insulin resistance syndrome." (PMID 27642517, 2016). "More recent evidence indicates that gut microbiota is also involved in the control of body weight and energy metabolism, affecting the two important causes of obesity: energy acquisition and storage, and contributing to insulin resistance and the inflammatory state characterizing obesity." (PMID 27317923, 2016). "Never the less, we recognize that it could be interesting to study the association with some other important risk factors, such as total and LDL cholesterol, insulin, hemoglobin glycated and inflammatory parameters in particular stratifying for obesity degree." (PMID 26732788, 2016). "However, in our studies such double-labelled BrdU/EdU insulin-positive beta cells were very rare, even in response to massive obesity-associated beta cell expansion." (PMID 27003683, 2016). "Chronic inflammation per se may be an important driver but other known risk factors, such as dyslipidemia, hypertension, insulin insensitivity, a physically inactive lifestyle, obesity, and tobacco smoking may also contribute substantially." (PMID 26738563, 2016). "In the future, it could be interesting to investigate whether transcriptional regulation of CiC and CACT is relevant in diseases associated with insulin signal deregulation, such as obesity and metabolic syndrome." (PMID 27231907, 2016). "Even though obesity is strongly associated to IR, it is now accepted that physically lean subjects may have defective insulin sensitivity and are candidates for IR screening." (PMID 27354200, 2016). "Effects of the dietary glycaemic load on postprandial blood glucose and insulin response might be of importance for fat deposition and risk of obesity." (PMID 26987056, 2016). "This is the first study that links the increment of CMKLR1 expression with insulin production, showing an association with fat mass and corporal dimensions, while the increased serum levels of chemerin in obesity were observed, favoring a dysmetabolic response." (PMID 27239101, 2016). "Obesity is also associated with higher serum insulin levels, and several prospective cohort studies have reported positive associations between circulating insulin levels and endometrial cancer risk." (PMID 27125830, 2016). "In addition, overnutrition by decrease in litter size on postnatal day 1 can lead to increased obesity susceptibility and insulin and leptin resistance after consumption of a HFD in later life." (PMID 27479001, 2016). "I further highlight published studies that suggest a role for insulin as a potential mediator by which obesity and cancer could be linked." (PMID 27604692, 2016). "Our results suggest that plasma AC and amino acids could serve as a gender-specific complex biomarker of propensity to obesity, however with a limited predictive value in case of the associated impairment of insulin sensitivity." (PMID 27183228, 2016). "Our findings argue against insulin playing a role in the hypogonadism associated with obesity." (PMID 25946091, 2015).
Obesity (continued). "Many possible mechanisms have been proposed to explain the increased risk of breast cancer associated with obesity such as increased lipids and lipid signaling, inflammatory responses, insulin resistance, adipokines, altered immune responses, and oxidative stress." (PMID 25923423, 2015). "Interestingly, SH2B1 is known to be involved in leptin and insulin signaling and has been reported as a predisposing factor for obesity." (PMID 26293599, 2015). "Human obesity is associated with altered dopamine (DA) function, altered DA D2-like receptor binding in brain reward regions, altered reward-related behavior, and insulin dysregulation." (PMID 26192187, 2015). "In line with this, and taking into account that obesity is associated to suppressed GH release, it seems reasonable to propose that other factors (leptin, insulin, adipokines, inflammatory factors, etc.)should contribute to the increased gene expression of GH/IGF-1 axis components." (PMID 25806796, 2015). "In girls, PAI-1 was associated with obesity, hypertriglyceridemia, and insulin secretion." (PMID 26633970, 2015). "The prevalence of hyperinsulinemia and IR rise with increasing body mass index and obesity, but whether insulin causes these phenomena or is a compensatory response has remained unsettled for decades." (PMID 25785277, 2015). "In addition, physical activity can reduce body fat and obesity by weight loss, which increase cellular insulin sensitivity and reverses IR caused by obesity." (PMID 27525252, 2015). "Both of these factors are thought to attenuate insulin action, in part, by activating pathways that interfere with or oppose insulin signaling and thus they have also been implicated in the development of obesity-induced IR." (PMID 25961014, 2015). "Obesity is marked by a complex metabolic phenotype that includes hyperinsulinemia and hyperleptinemia, with insulin and leptin resistance that each could contribute to the reproductive dysfunction associated with obesity." (PMID 25780937, 2015). "We therefore tested the hypothesis that chronic DEHP exposure causes impaired insulin sensitivity, affects body weight, adipose tissue (AT) function and circulating metabolic parameters of obesity resistant 129S6 mice in vivo." (PMID 26630026, 2015). "Adipokines can influence insulin sensitivity, and the regulation of adipokines may play a pivotal role in the aetiology of IR, which is associated with obesity and cardiovascular disease." (PMID 25878729, 2015). "Obesity and high insulin levels are often associated with fatty liver in humans." (PMID 26077675, 2015). "Second, the significance of hypothalamic microglia and astrocytes in pathological metabolic processes associated with obesity, such as hypothalamic inflammation and related insulin and leptin resistance, has become increasingly evident in rodent and human disease models." (PMID 26491443, 2015). "Our purpose was to determine whether these mitochondrial readouts are associated with obesity, body composition, body fat distribution and insulin sensitivity in older men and women." (PMID 26448868, 2015). "Thus, obesity is associated with a low-grade inflammation, which derives from excessive lipid deposition and inhibits insulin signaling, namely, in muscle, liver, and adipose tissues." (PMID 26075283, 2015). "Hyperinsulinemia is strongly associated with obesity, but whether insulin drives obesity or is simply a compensatory response to obesity-driven insulin resistance remains unknown." (PMID 26225266, 2015). "Authors hypothesized that obesity may be linked with the development of irisin resistance, similarly to what is observed for insulin and leptin." (PMID 26075283, 2015). "Thus, the children even if at early stage of childhood with relatively higher fasting insulin levels should be given more attention to prevent the development of obesity and the accumulation of risk factors of a potential metabolic syndrome." (PMID 26047327, 2015).
Obesity (continued). "In addition, FGF21 alleviates the major risk factors of NAFLD, including obesity, dyslipidemia, and insulin insensitivity." (PMID 26441837, 2015). "Also in this context, there are proposed influences of adipokines, such as leptin and adiponectin, and also insulin, on central mechanisms of energy balance, causing irreversible changes in hypothalamic neural interconnections leading to obesity and cancer." (PMID 25874125, 2015). "Although only leptin is secreted by the adipocyte cell, both, insulin and leptin, are the predominant adiposity signals in circulation, and therefore were chosen to assess the effects of obesity associated endocrine signals in prostate cancer cell proliferation." (PMID 25928422, 2015). "Overall, the role of IL-6 in insulin sensitivity and glucose homeostasis remains controversial; and we speculate that the obesity-associated perturbations in IL-6 and its receptor likely have diverse effects in different tissues and organs." (PMID 26200663, 2015). "Adiponectin is a strong indicator of insulin sensitivity wherein its decline precedes the onset of obesity and insulin resistance and may be one mechanism through which obesity alters BC risk." (PMID 25838618, 2015). "The association of low birth weight and subsequent obesity is explained by the programming or the fetal insulin hypothesis." (PMID 24633695, 2015). "Moreover, the rs8192673 of the PGC-1α gene was reported to be associated with insulin resistance, obesity indices in women and with lipid metabolism and insulin secretion." (PMID 25928419, 2015). "Obesity is the primary risk factor for the development of type 2 diabetes by causing inulin resistance, which results in a greater demand of the pancreas to secrete insulin and eventually β-cell failure in susceptible individuals." (PMID 25835281, 2015). "Therefore, men are more susceptible than women to the consequences of indolence and obesity, possibly due to differences in insulin sensitivity and regional fat deposition." (PMID 26322779, 2015). "In summary, there is close reciprocal relationship between obesity-associated elevations in insulin/IGF and inflammatory signaling, such that both factors should be considered in the development of interventions to improve cancer prevention and treatment in the obese patient population." (PMID 26029167, 2015). "Reduced vessel density in adipose tissue and skeletal muscle is associated with obesity and may result in decreased perfusion, decreased oxygen consumption, and insulin resistance." (PMID 26038468, 2015). "Target prediction and function annotation of associated genes revealed that these genes were predominantly involved in metabolic, insulin signaling, and adipocytokine signaling pathways that directly link the pathophysiological changes associated with obesity and weight reduction." (PMID 26377847, 2015). "Moreover, loss of TNF-α in obesity resulted in improved insulin sensitivity and glucose homeostasis." (PMID 25157251, 2014). "One of several mechanisms in which the insulin sensitivity is lost in obesity is due to the increase production of nitric oxide (NO), particularly as a result of inducible nitric oxide synthase (iNOS), which has also been associated with resistance to insulin." (PMID 24979131, 2014). "Moreover, dietary n-3 PUFA have been found to reverse and/or improved obesity-associated hepatic steatosis and impairments in glucose metabolism and insulin sensitivity." (PMID 25360510, 2014). "Our findings suggest that obesity-driven factors such as HGF/c-Met, insulin, and the leptin:adiponectin ratio may contribute to the onset of obesity-promoted BBCs, and that weight loss prior to tumor onset may prevent tumor progression." (PMID 25072025, 2014).
Obesity (continued). "Among them, mutations in the leptin gene (ob/ob mice) or in the leptin receptor gene (db/db mice, fa/fa rats), leading to the deficiency of the related proteins, produce extreme obesity in rodents as well as in humans, due to hyperphagia, decreased energy expenditure, and insulin-resistance." (PMID 25352831, 2014). "Hyperinsulinaemia and hyperleptinaemia are associated with increased seminal insulin and leptin concentrations, which may negatively impact male reproductive function in obesity." (PMID 24885899, 2014). "We hypothesized that a loss of DUSP2 function would reduce obesity-associated inflammation and, consequently, would improve insulin sensitivity in mice fed a HFD." (PMID 25375135, 2014). "Obesity is associated with an increased infiltration of macrophages into adipose tissue and an inverse correlation between the number of macrophages present in the adipose tissue and insulin sensitivity was shown." (PMID 25233471, 2014). "One version is that obesity causes an increase in visceral fat mass that secretes free fatty acids and inflammatory cytokines into the hepatic portal vein, leading to peripheral insulin resistance." (PMID 26237598, 2014). "This acute reaction to a HF diet in terms of glucose intolerance and the acute phase response may be indicative of a susceptibility to developing obesity and insulin insensitivity." (PMID 25170916, 2014). "Obesity is a risk factor for osteoarthritis and the growth in fat mass is directly proportional to exaggerated consumption of nutrients, especially saturated fatty acids, responsible for low grade inflammation and central resistance to insulin and to leptin." (PMID 25184806, 2014). "Consequently, the ALCAT1 deficiency prevented the onset of diet-induced obesity and significantly improved mitochondrial complex I activity, lipid oxidation, and insulin signaling in ALCAT1−/− mice." (PMID 25415055, 2014). "However, a limited number of data exist on the association between thyroid function and insulin activity in euthyroid subjects, especially when considering the influence of obesity." (PMID 24872812, 2014). "High serum BCAA (especially leucine) concentrations were associated with obesity and hyperinsulinemia, a finding that is consistent with earlier studies suggesting that BCAAs may augment the pancreatic secretion of insulin in the IR state." (PMID 25260659, 2014). "According to the hypothesis, such epigenetic changes may predispose to insulin dysregulation, obesity, and T2D in later life." (PMID 24744783, 2014). "Moreover, treatment for obesity with bariatric surgery or metformin increases serum level of omentin, which is associated with weight loss and improved insulin sensitivity, possibly through activating Akt signaling pathway." (PMID 24899788, 2014). "However, under the influence of physiological conditions associated to obesity, such as chronic inflammation and hypoxia, insulin sensitivity would finally be compromised." (PMID 24751908, 2014). "It is suggested that by more than one mechanism the obesity can produce a wide range of abnormalities in carbohydrate and lipid metabolism, insulin resistance, and adipocyte hormone action and may cause congenital defects." (PMID 25562026, 2014). "Thus, MK is a novel adipocyte-secreted factor associated with obesity and inhibition of insulin signaling in adipocytes." (PMID 24516630, 2014). "Recently, the therapeutic effects of central leptin gene therapy have been reported in insulin-deficient diabetes in obesity animal models such as ob/ob mise, diet-induced obese mice, and insulin-deficient type 1 diabetes mice, and also in patients with inactivating mutations in the leptin gene." (PMID 23579596, 2013). "Therefore, understanding the molecular and cellular mechanisms underlying energy balance, glucose, and insulin homeostasis is critical for developing new strategies for the prevention and treatment of metabolic syndromes including obesity and diabetes." (PMID 23675313, 2013).